ZNF740 (zinc finger protein 740)
Description:
May be involved in transcriptional regulation.
Synonyms: Zfp740
Tractability: PROTAC: UniProt records ubiquitination sites on it; ubiquitination databases record sites on it; its protein half-life has been measured.
Gene: Protein-coding gene on chromosome 12 (53,180,694 to 53,195,142, forward strand). Ensembl gene ENSG00000139651.
Subcellular location: Nucleus
Subcellular location (Human Protein Atlas): Nucleoplasm
Pathways (Reactome):
Gene expression (Transcription): Generic Transcription Pathway
Gene Ontology:
Molecular function: protein binding; sequence-specific double-stranded DNA binding; DNA-binding transcription factor activity; DNA-binding transcription factor activity, RNA polymerase II-specific; RNA polymerase II cis-regulatory region sequence-specific DNA binding
Biological process: regulation of transcription by RNA polymerase II
Cellular component: chromatin; nucleus
Genetic constraint (gnomAD): Loss-of-function variants: 14 observed, 22.34 expected, observed/expected ratio (o/e) 0.63, 90% interval 0.41 to 0.98. The upper end of that interval is the gene's LOEUF score, 0.98, which puts it in group 4 of 6, group 1 being the genes least tolerant of losing a copy. Missense variants: 201 observed, 240.67 expected, observed/expected ratio (o/e) 0.84, 90% interval 0.74 to 0.94. Synonymous variants: 69 observed, 82.15 expected, observed/expected ratio (o/e) 0.84, 90% interval 0.69 to 1.03.
Homologues: Orthologues: dog ZNF740 (98% identical), macaque ZNF740 (98% identical), pig ZNF740 (98% identical), chimpanzee ZNF740 (87% identical), rabbit ZNF740 (85% identical), guinea pig ZNF740 (84% identical), mouse Zfp740 (69% identical), rat Znf740 (67% identical), tropical clawed frog znf740 (50% identical), zebrafish znf740b (49% identical), Caenorhabditis elegans klu-2 (20% identical), Drosophila melanogaster klu (20% identical), and 1 more. Paralogues in human: ZBTB7A (22% identical), ZNF367 (19% identical), ZBTB5 (17% identical), ZBTB43 (17% identical).
Diseases named in the same sentence as ZNF740 in open-access papers:
ZNF740 is named in the same sentence as 6 diseases in open-access papers, as found by Europe PMC text mining. Sharing a sentence is not in itself a finding about the gene and the disease. The quoted sentences say what the papers report.
heart failure (1 paper, 2024). Inability of the heart to pump blood at an adequate rate to meet tissue metabolic requirements. "ZNF740 is a transcriptional regulator whose DNA binding motifs are associated with enhancer usage in heart failure suggesting that this gene may indeed play a role in cardiotoxicity." (PMID 38416769, 2024).
prostate carcinoma (1 paper, 2025). A carcinoma that arises from epithelial cells of the prostate gland. "The first cluster is composed of ZNF740, AR, and TBX5, which are implicated in prostate cancer." (PMID 40453647, 2025).
ZNF740 also shares sentences with these, for which no sentence is quoted: tuberculosis (2 papers); hepatic carcinoma (1); infection (1); tumor (1).